SNORD46 (small nucleolar RNA, C/D box 46)
Synonyms: U46; U40; RNU40; RNU46
Gene: Small nucleolar RNA gene on chromosome 1 (44,776,490 to 44,776,593, forward strand). Ensembl gene ENSG00000200913.
Gene Ontology:
Biological process: RNA processing
Cellular component: nucleolus
Homologues: Orthologues: chimpanzee SNORD46 (100% identical), macaque SNORD46 (99% identical), rat Snord46 (95% identical), mouse Gm26330 (91% identical), rabbit SNORD46 (89% identical), pig SNORD46 (88% identical), guinea pig SNORD46 (86% identical), zebrafish SNORD46 (70% identical).
Diseases named in the same sentence as SNORD46 in open-access papers:
SNORD46 is named in the same sentence as 7 diseases in open-access papers, as found by Europe PMC text mining. Sharing a sentence is not in itself a finding about the gene and the disease. The quoted sentences say what the papers report.
Obesity (1 paper, 2023). Accumulation of substantial excess body fat. "Interestingly, SNORD46 mutant mice led to improved glucose tolerance, decreased body weight, reduced liver steatosis and fatty acid accumulation, and decreased lipid accumulation in the liver, demonstrating that modifying SNORD46 may yield anticancer properties and anti-obesity properties." (PMID 37626871, 2023).
cancer (4 papers, 2019 to 2022). A tumor composed of atypical neoplastic, often pleomorphic cells that invade other tissues. "A pancancer study demonstrated general upregulation of snoRNAs in 13 cancer types and proved that enhanced expression of SNORD46 promotes proliferation, migration and invasion of cancer cells." (PMID 34884928, 2021). "A recent global analysis of the expression of snoRNAs in 31 different cancer types showed that the snoRNA expression is generally decreased in tumors when compared to normal tissues and identified SNORD46 as a tumor suppressor." (PMID 31039818, 2019). "SNORD46 is upregulated in multiple types of cancer, whereas inhibition of SNORD46 in A549 cells led to a decrease in cell viability, migration and tissue invasion, suggesting an oncogenic role for SNORD46 in pediatric BCP-ALL." (PMID 35740251, 2022). "Functional enrichment showed that the co-expressed genes of SNORD46, SNORD 124 can be significantly enriched in some well-known cancer-related pathways, such as the spliceosome and Notch signaling pathways." (PMID 36181013, 2022).
tumor (4 papers, 2019 to 2024). "Among them, they identified SNORD46 as down-regulated in tumor tissues." (PMID 38534323, 2024). "We identified 42 DEs and established 6 survival-related snoRNAs using Cox analysis: 2 of the 6 snoRNAs, SNORA16B and SNORD63, are protective factors, and the other 4 (SNORA59B, SNORD11, SNORD46, and SNORD 124) are risk factors that may play a crucial role in tumor metastasis and progression." (PMID 36181013, 2022).
SNORD46 also shares sentences with these, for which no sentence is quoted: autism spectrum disorder (1 paper); liver (1); osteoarthritis (1); steatosis (1).